CXCR4 (C-X-C motif chemokine receptor 4)
Diseases named in the same sentence as CXCR4 in open-access papers (continued):
Sharing a sentence is not in itself a finding about the gene and the disease.
viral infection (continued). "Because CXCR4-using viruses are considered as T-tropic and rarely M-tropic, as shown using cell-free virus infection assays, we interrogated whether they could be transferred from infected T cells to MΦ by cell-cell fusion." (PMID 35622876, 2022). "Intriguing examples such as GPR35 for inflammatory bowel disease and CXCR4 for viral infection are used as illustrations of how a systematic approach can aid in the prioritization of interesting drug discovery hypotheses." (PMID 30285606, 2018). "Importantly, R3A-5/6AA replicated to the same level as wild type R3A by using CXCR4 for viral infection." (PMID 27026376, 2016). "Given that direct antagonism of chemokine receptor function can block viral infection, it is possible that allosteric modulation of CXCR4 through a GPCR partner may also reduce HIV-1 permissiveness." (PMID 22448282, 2012). "In this context, it has been shown that HIV-derived Tat and gp120 proteins increase the expression and release of CCL2, which may facilitate the viral infection by upregulating the expression of CXCR4 (a co-receptor for HIV) and the recruitment of target cells to infection sites." (PMID 37999614, 2023). "We identified 31 differentially expressed circRNAs and 7 mRNAs (HSPA8, HSPA1B, EGR2, CXCR4, SOCS3, NOTCH3, and ZNF527) related to viral infection." (PMID 41471859, 2025). "The chemokine co-receptors CXCR4 and CCR5 mediate HIV entry and signal transduction necessary for viral infection." (PMID 39146384, 2024). "These chemokines include SDF-1α, MCP-2, MCP-4, MIP-1α, and Eotaxin-1, which bind either to CXCR4, CXCR5, CCR5, or CCR3 and regulate viral infection." (PMID 36851142, 2023). "In a pre-existing Mtb infection, specifically within the granuloma, HIV encounters a highly permissive CD4+ T lymphocyte population expressing the membrane receptors required for viral infection (CD4, CCR5, or CXCR4)." (PMID 37110276, 2023). "The previous study showed that CRISPR/Cas9 targeting CXCR4 or CCR5 chemokine receptors, the co-receptors for HIV-1, protected the primary CD4+ T cells from viral infection." (PMID 36499376, 2022). "During an acute virus infection, TFR-derived IL-10 is important for regulating Foxo1 activity and the capacity of GC B cells to down-regulate CXCR4 and cycle between the DZ and LZ of the GC." (PMID 33529242, 2021). "On the contrary, only the iridoid glycoside 2′-O-(4-methoxycinnamoyl) mussaenosidic acid, isolated from Avicenna marina, has been reported for its ability to prevent viral infection, acting on co-receptors CCR5 and CXCR4." (PMID 34443358, 2021). "As the HIV-1 envelope protein, gp120 is critical for virus infection, because it is necessary for binding to specific cell surface receptors (CD4, CXCR4, and CCR5) on target cells and facilitating virus entry." (PMID 31379513, 2019). "Detection of R5-tropic virus infection in CD4+ T lymphocytes was lower than that of X4-tropic virus infection, which should be due to a lower level of CCR5 expression than CXCR4 expression in CD4+ T lymphocytes." (PMID 28241053, 2017). "Due to the variation in viral infection, co-disruption of CCR5 and CXCR4 should be tested using lenti- or adenovirus mediated CRISPR/Cas9 system in the future." (PMID 26481100, 2015). "Chemokine receptors such as CCR5 and CXCR4 play a major role in HIV-entry into target cells and viral infection." (PMID 24571616, 2014). "To address the role of PGE2 in RT activity and viral DNA integration, we used a single virus infection cycle with HIV-1 VSV-Luc, which enters cells via endocytosis and thereby bypasses CD4/CXCR4 and the cortical actin." (PMID 24586238, 2014). "Because there were so few cases of purely X4 virus infection, the tropism was dichotomized as either a CCR5- or CXCR4-using virus." (PMID 23226258, 2012). "The human chemokine receptors CXCR4 and CCR5 are members of the rhodopsin family of GPCRs, which are unrelated to the TAS2Rs and are involved in inflammation, autoimmune disease, and viral infection." (PMID 21629661, 2011).
viral infection (continued). "The fact that both CXCR4 and CCR5 are chemokine receptors raised interesting questions regarding the role of chemokine receptor signaling in viral infection and pathogenesis." (PMID 20041213, 2009). "The kinetics of both CXCR4 tropic and CCR5 tropic virus infection were analyzed for virus-cells preincubated at 23°C-TAS compared to those preincubated at 4°C." (PMID 16725045, 2006). "This cell line contains both CXCR4 and CCR5 and permits low-level R5 viral infection." (PMID 39146384, 2024). "CXCR4 expression also increased modestly in CAR pNK cells, indicating endogenous CXCR4 upregulation was not induced by viral infection." (PMID 38979422, 2024). "Additionally, DEGs related to the response to viral infections, such as DDIT4, CXCR4, EIF5A, TNFAIP3, BCL2, and IRF1, were also upregulated in NBs." (PMID 38440735, 2024). "To confirm that the decrease in CXCR4 expression was specifically responsible for the lack of X4-tropic viral infection in JunB KO 1–6 cells, we recovered CXCR4 expression by transfection of a CMV-driven CXCR4 expression plasmid." (PMID 38835488, 2024). "As JunB is a transcription factor, we hypothesized that the absence of JunB may alter the expression of host factors required for viral infection, such as CD4 or CXCR4." (PMID 38835488, 2024). "Thus, IL-2 enhanced the magnitude of HIV replication in TFH, TFH survival, and particularly GFP+ TFH survival in both CXCR4-tropic and CCR5-tropic virus infection." (PMID 36420277, 2022). "Given the fact that CXCR4 plays a relevant function in HIV entry, suppression of CXCR4 could simultaneously counteract both mycobacterial and viral infection." (PMID 28332618, 2017). "We have examined the effects of US27 on CXCR4 here using transfected proteins, in the absence of virus infection." (PMID 28207860, 2017). "We took advantage of a mutant R3A strain termed R3A-5/6AA from the study, which has lost the ability to bind and utilize CCR5 but can still use CXCR4 for viral infection, therefore not affecting viral replication capability." (PMID 27026376, 2016). "To quantitatively test whether alteration of CXCR4 could confer protection to Ghost X4 cells, we analyzed the percentage of GFP positive cells by flow cytometry 4 days after viral infection." (PMID 26481100, 2015). "These proteins, members of the CXCR4 signalling pathway, differentially expressed when comparing HPAI- and LPAI-infection, play a role in different virus infection or in immune response and might have a role in the difference of influenza virulence in ducks." (PMID 24015922, 2013). "Unlike cell-free viral infection, transfer of virus between cells is co-receptor independent; blockade of viral binding to CXCR4 with a selective antagonist, AMD3100, does not inhibit passage of virus." (PMID 22448282, 2012). "Gp120 is critical for virus infection, as the protein is necessary for binding to specific cell surface receptor CD4, mainly expressed on CD4+ T cells, and the coreceptor [e.g., chemokine receptor C-C Motif Chemokine Receptor 5 (CCR5) or C-X-C chemokine receptor type 4 (CXCR4)]." (PMID 36093171, 2022). "Ample viral gene expression in memory cells devoid of multiple T cell activation surface markers indicates that an activated state is not required for productive CCR5-tropic virus infection, corroborating several previous studies primarily investigating CXCR4-tropic virus." (PMID 28654687, 2017). "In order to determine whether Env mutants with PNGS mutations could be incorporated into viral particles and support viral infection, we generated pseudoviruses with the PNGS mutants of Env and tested the capacity of these pseudoviruses to infect TZM-bl cells (CD4+, CCR5+, and CXCR4+)." (PMID 23384254, 2013). "Also immune activation leads to an up regulation of co-receptors, both CXCR4 and CCR5, that not only facilitate virus infection but may also enhance Env mediated apoptosis." (PMID 23202514, 2012).
viral infection (continued). "Recent evidence has emerged implicating chemokines, specifically CXCR4 and CXCL12, as important mediators of neurogenesis; thus, chemokines produced during viral infections may influence neural precursor cell function and therefore influence recovery and repair." (PMID 20686655, 2010).
lymph node metastasis (77 papers, 2005 to 2025). "Retrospective clinical analyses underscore the prognostic significance of CXCR4, as its overexpression correlates with increased lymph node metastasis risk, including micrometastases." (PMID 40134607, 2025). "Sixteen studies including 1795 patients showed a statistically significant association between CXCR4 expression and lymph node metastasis (OR 2.35, 95% CI 1.90–2.90, P < 0.001)." (PMID 35729596, 2022). "It is possible that the impact of the CXCR4/SDF-1 axis is more prominent in patients with lymph node metastasis, or after recurrence, as this pathway is implicated in cell migration, invasion, and possible homing to different organ sites of metastases." (PMID 33507926, 2021). "In the present study, our data demonstrate that CXCR4 expression is associated with lymph node metastasis of lung adenocarcinoma in the cohort examined." (PMID 32368286, 2020). "CXCR4 expression was significantly associated with lymph node metastasis (P = 0.001), and EGFR/CXCR4 coexpression was significantly associated with lymph node metastasis (P = 0.026), TNM stage (P = 0.048), and poor tumor differentiation (P = 0.004)." (PMID 25679210, 2015). "The CXCR4 expression was correlated with lymph node metastasis, and the expression intensity of CXCL12 was associated with the volume of ascites." (PMID 24765180, 2014). "High CXCR4 expression has been associated with lymph node metastases in breast cancer and oral squamous cell carcinoma." (PMID 23761820, 2013). "High VEGF-C and CXCR4 expression levels in hepatocellular carcinoma have also been associated with lymph node metastasis." (PMID 23761820, 2013). "The authors theorized that CCR7 is associated with lymph node metastasis, while CXCR4 expression aids in the reliability of CCR7 as a biomarker." (PMID 22295222, 2011). "Cytoplasmic CXCR4 expression is significantly associated with lymph node metastasis and high nitrotyrosine levels." (PMID 19025611, 2008). "The CXCR4/CXCL12 axis is significantly associated with lymph node metastasis and poor prognosis." (PMID 41445742, 2025). "CXCR4 expression is also linked to lymph node metastasis and poor prognosis." (PMID 40134607, 2025). "In addition, multiple studies have shown that CXCR4 expression is frequently upregulated in oral squamous cell carcinomas (OSCCs) and that high CXCR4 expression is associated with lymph node metastasis, tumor recurrence, and a poor prognosis." (PMID 36300800, 2023). "Moreover, CXCR4 is also correlated with poor histological differentiation, distant metastasis and lymph node metastasis, being its higher levels associated with poor prognosis in CRC patients." (PMID 35053143, 2022). "In summary, the present study demonstrated that CXCR4 was upregulated and associated with lymph node metastasis, and exo-hsa_circRNA_0056616 in plasma to serve as a potential biomarker for theragnostic of lymph node metastasis in lung adenocarcinoma." (PMID 32368286, 2020). "Moreover, high CXCR4 expression has been found to be an independent prognostic biomarker associated with lymph node metastases and distant metastatic recurrence in resected PDAC." (PMID 25679210, 2015). "Furthermore, strong CXCR4 expression was significantly associated with lymph node metastases, higher UICC stages and a reduced 5-year survival rate." (PMID 20386750, 2010). "For example, the presence of circRNA in exosomes (exo-hsa_circRNA) was found to be associated with CXCR4 expression which was confirmed to be related to the lymph node metastasis of lung adenocarcinoma in vivo, so it may be a predictor of lymph node metastasis in lung adenocarcinoma." (PMID 35505392, 2022). "In addition, other reports have observed that the expression of CXCR4 is associated with the clinical stage, lymph node metastasis, and liver metastasis which could assist in determining the prognosis." (PMID 29887884, 2018).
lymph node metastasis (continued). "Multivariate analysis revealed that age, tumor length, differentiation, lymph node metastasis, and CXCR4 expression are independent prognostic factors in LUAD (P < 0.05)." (PMID 36308553, 2023). "The mean mRNA expression level of CXCR4 in patients with lymph node metastases was significantly higher than in the N0 group (p = 0.0237)." (PMID 35877436, 2022). "The results supported that CXCR4 expression is correlated with lymph node metastasis, distant metastasis, tumor stage, and OS." (PMID 34722241, 2021). "The univariate Cox proportional hazards method demonstrated the prognostic value of lymph node metastasis, stage, CXCR-4, PKC-δ and CD133 in oral squamous cell carcinoma." (PMID 34885003, 2021). "Particularly, the expression of CXCR-4 has been found to be higher in lymph node metastasis-positive cases when compared to lymph node metastasis-negative cases." (PMID 34885003, 2021). "In both cohorts, HOXB5 expression positively correlated with CXCR4 and ITGB3 expression, and elevated expression of CXCR4 and ITGB3 positively associated with lymph node metastasis, distant metastasis and advanced AJCC stage." (PMID 33456563, 2021). "The relationships between CXCR4 expression and patient clinicopathological features, including sex, age, lymph node metastasis, tumour differentiation and invasion depth, were also analysed." (PMID 33052232, 2020). "Clinically, high CXCR4 expression was significantly associated with solid ASC, lymph node metastasis and advanced TNM stage." (PMID 31949484, 2020). "Together, these results suggest that overexpression of CXCR4 in lung adenocarcinoma is related to lymph node metastasis." (PMID 32368286, 2020). "It has been shown that lymph node metastasis and distant organ metastasis frequently occurred in CXCR4-positive tumor cases; thus, CXCR4 is considered to be a factor of poor prognosis in cancer." (PMID 31336612, 2019). "High expression of CXCR4 in resected PDA has been associated with shorter overall survival, lymph node metastases, and liver recurrence in a small series of patients." (PMID 25050350, 2014). "Elevated CXCR4 expression is related to vascular invasion, lymph node metastasis, and the TNM stages." (PMID 25471741, 2014). "Gastric cancer, which exhibited a co-expression of CCR7 and CXCR4, was revealed to be more likely to include lymph node metastasis." (PMID 23761820, 2013). "High protein expression of HIF-2α, TWIST, and CXCR4 was significantly correlated with lymph node metastasis (LNM) (P < 0.001)." (PMID 24288553, 2013). "Results showed a lymph node metastasis rate of 79% with tumors expressing high levels of both CXCR4 and VEGF compared with a 45% rate when only one of these factors is high (P = 0.007)." (PMID 22295222, 2011). "Cytoplasmic CXCR4 significantly correlated with nitrotyrosine levels, lymph node metastasis, and distant metastasis." (PMID 22295222, 2011). "Immunohistochemical analyses have shown that specific patterns of CXCR4 expression (i.e., in the nucleus or cytoplasm) are correlated with a high nuclear grade or lymph node metastasis." (PMID 22220212, 2011). "In contrast, CXCR4 mRNA expression levels were significantly higher in lymph node metastasis group (15.91 ± 12.14 fold) and distant metastasis group (23.20 ± 14.84 fold) than in normal colonic tissue (6.23 ± 4.66 fold)." (PMID 20953377, 2010). "Detection of CXCR4 positive microvessels in large lymph node metastases (>9 mm in diameter) corroborated these observations." (PMID 20386750, 2010). "One study determined that the CXCR4 expression pattern correlated significantly with the degree of lymph node metastasis by investigating CXCR4 expression in 79 cases of invasive duct cancer (IDC)." (PMID 20181250, 2010).